TPMT (thiopurine S-methyltransferase)
Description:
Catalyzes the S-methylation of thiopurine drugs such as 6-mercaptopurine (also called mercaptopurine, 6-MP or its brand name Purinethol) and 6-thioguanine (also called tioguanine or 6-TG) using S-adenosyl-L-methionine as the methyl donor. TPMT activity modulates the cytotoxic effects of thiopurine prodrugs. A natural substrate for this enzyme has yet to be identified.
Synonyms: TPMTD
Tractability: Small molecule: a structure with a bound ligand is known; a high-quality ligand is known; it has a high-quality binding pocket; it belongs to a druggable protein family. PROTAC: ubiquitination databases record sites on it; its protein half-life has been measured; a small molecule that binds it is known.
Target class: Enzyme; Transferase
Safety:
Unwanted effects reported when the protein is acted on. In parentheses: how it was acted on, where the effect was seen, and who reports it.
adverse events (source: ClinPGx)
drug toxicity (source: ClinPGx)
fatigue (source: ClinPGx)
GI toxicity (source: ClinPGx)
hearing loss (source: ClinPGx)
ototoxicity (source: ClinPGx)
severe rejection (source: ClinPGx)
Gene: Protein-coding gene on chromosome 6 (18,128,311 to 18,155,348, reverse strand). Ensembl gene ENSG00000137364.
Subcellular location: Cytoplasm
Pathways (Reactome):
Disease: Defective TPMT causes TPMT deficiency
Drug ADME: Azathioprine ADME
Metabolism: Methylation
Gene Ontology:
Molecular function: protein binding; S-adenosyl-L-methionine binding; thiopurine S-methyltransferase activity; S-adenosylmethionine-dependent methyltransferase activity
Biological process: xenobiotic metabolic process; methylation; nucleobase-containing compound metabolic process; xenobiotic catabolic process
Cellular component: cytosol; cytoplasm
Genetic constraint (gnomAD): Loss-of-function variants: 19 observed, 33.89 expected, observed/expected ratio (o/e) 0.56, 90% interval 0.39 to 0.82. The synonymous counts are far from expectation, so gnomAD's model fits this gene poorly and the ratio says little. Missense variants: 256 observed, 276.49 expected, observed/expected ratio (o/e) 0.93, 90% interval 0.83 to 1.03. Synonymous variants: 66 observed, 90.66 expected, observed/expected ratio (o/e) 0.73, 90% interval 0.6 to 0.89.
Homologues: Orthologues: chimpanzee TPMT (99% identical), macaque TPMT (93% identical), rabbit TPMT (84% identical), dog TPMT (81% identical), pig TPMT (81% identical), mouse Tpmt (77% identical), rat Tpmt (77% identical), guinea pig TPMT (75% identical), zebrafish tpmt.1 (49% identical), tropical clawed frog tpmt (48% identical), zebrafish tpmt.2 (48% identical).
Diseases named in the same sentence as TPMT in open-access papers:
TPMT is named in the same sentence as 107 diseases in open-access papers, as found by Europe PMC text mining. Sharing a sentence is not in itself a finding about the gene and the disease. The quoted sentences say what the papers report.
leukopenia (54 papers, 2015 to 2026). "In an Indian inflammatory bowel disease cohort, carriers of NUDT15 c.415C>T faced a nearly 19-fold higher risk of leukopenia, while TPMT variants were rare." (PMID 41446785, 2025). "The prescribed moderate dose of AZA (66 mg/m2) in a poor TPMT metabolizer can cause leukopenia itself." (PMID 40558232, 2025). "Although additional validation through larger prospective studies or meta-analyses is needed, our findings support the importance of TPMT gene-variant assessment for forecasting azathioprine-related leukopenia in Italian IBD patients." (PMID 40869181, 2025). "CD patients with leukopenia had a higher frequency of the TPMT risk haplotype (40% vs. 4%, p = 0.024)." (PMID 40869181, 2025). "The TPMT * 2 genotype, with a prevalence of 0.2–0.5%, is significantly more associated with AZA-induced leukopenia, followed by an unusual prevalence of TPMT * 3B, found in Chinese, Ghanaian, and Japanese populations." (PMID 37959208, 2023). "Several studies have pointed out that patients with polymorphisms in the TPMT gene related to decreased enzymatic activity are at greater risk of thiopurine-induced leukopenia." (PMID 37959208, 2023). "Among the studies evaluated in this review, 21 (52%) directly correlated TPMT polymorphisms with the occurrence of adverse effects, particularly leukopenia, bone marrow toxicity, hepatotoxicity, pancreatitis, nausea, and vomiting." (PMID 37959208, 2023). "TPMT enzyme mutants with reduced activity are associated with life-threatening thiopurine-induced leukopenia in approximately 5% of patients of European descent." (PMID 36768780, 2023). "Patients with reduced TPMT activity are more susceptible to adverse reactions (AEs), such leukopenia, hepatotoxicity, pancreatitis, and nausea, which are common adverse effects of thiopurine therapy." (PMID 37959208, 2023). "In meta-analysis studies, TPMT*3C variant is known to be associated with an increased risk in thiopurine-induced leukopenia in European descendants." (PMID 35548363, 2022). "Loss of the TPMT function leads to excessive levels of 6-TGNs, which greatly increase the risk of leukopenia." (PMID 36238550, 2022). "Screening for reduced thiopurine S-methyltransferase (TPMT) activity is common practice for identifying and excluding patients with increased risk of leukopenia." (PMID 36465944, 2022). "For instance, Uchiyama found that the ITPA 94C > A mutation occurred more frequently than TPMT variants in Japanese patients diagnosed with thiopurine-induced leukopenia." (PMID 36238550, 2022). "Children with the TPMT*1/*3C genotype had a higher risk of leukopenia with an odds ratio (OR) of 4.10 (95% confidence interval (CI) of 1.06–15.94; p = 0.033) compared to wild type (TPMT*1/*1) patients." (PMID 34442427, 2021). "Comparison regarding incidence of leukopenia and maximum tolerated thiopurine dosage was performed between those with wild polymorphism and those with TPMT and NUDT15 polymorphisms, respectively." (PMID 34425754, 2021). "Thiopurine-associated leukopenia (more than 30%) was found to be considerably higher than expected according to the frequency of the TPMT variant (~1%) in Koreans with Crohn’s disease." (PMID 33430289, 2021). "In Western countries, polymorphisms in TPMT gene have been recognized as the important cause of thiopurine related leukopenia." (PMID 34425754, 2021). "NUDT15 polymorphism was more frequent than TPMT polymorphisms and was associated with thiopurine induced leukopenia." (PMID 34425754, 2021). "As the number of leukopenia events is strongly associated with TPMT and NUDT15 variants, we also subdivided the sample according to the presence or absence of TPMT and/or NUDT15 variants." (PMID 33424606, 2020). "Single-nucleotide polymorphism (SNP) in TPMT (i.e., rs1142345) was first identified as a pharmacogenetic marker through pharmacology-guided approach, explaining the majority of 6MP-induced leukopenia cases in Caucasians and Africans." (PMID 32265697, 2020).
leukopenia (continued). "Genetic polymorphism of thiopurine S-methyltransferase (TPMT) causing TMPT deficiency is a well-established genetic marker of thiopurine-induced leukopenia in Caucasians." (PMID 29923122, 2018). "Although loss of function of TPMT is a robust predictor of thiopurine-induced leukopenia, quite a few patients who are wild type for TPMT still develop toxicity that requires 6-MP dose reduction or treatment interruption." (PMID 29720126, 2018). "Lower activity of the enzymes that inactivate thiopurines, such as thiopurine S-methyltransferase (TPMT), leads to higher production of 6-TGNs or other metabolites, causing dose-dependent adverse reactions typified by leukopenia." (PMID 29192347, 2018). "TPMT deficiency causes increasing 6-TGN levels related to leukopenia and increasing 6-methylmercaptopurine (6-MMP) levels and 6-MMPR levels related to hepatotoxicity." (PMID 29192347, 2018). "In our study, there were four patients (4.6%) who carried heterozygote mutant allele of TPMT*3C and only one patient (4.3%) with leukopenia carried TPMT variant alleles, however 22 patients (26.5%) with TPMT*3C wild type suffered leukopenia." (PMID 29867468, 2018). "This study aimed to determine the relationship between thiopurine metabolite levels and therapeutic response, and to investigate the association of NUDT15, TPMT, and thiopurine metabolites with leukopenia in patients with CD." (PMID 29206869, 2017). "Univariable analysis showed that concurrent use of 5-ASA, presence of leukopenia, azathioprine/mercaptopurine weight-based dosage, and TPMT variant genotype were significantly associated with 6-TGN levels." (PMID 29206869, 2017). "Thiopurine-induced leukopenia has been primarily explained by TPMT variants that induce the intracellular 6-TGN accumulations." (PMID 29206869, 2017). "The aim of this study was to assess the association between thiopurine metabolite levels and therapeutic response and to evaluate the association of NUDT15, TPMT, and metabolites of thiopurines with leukopenia in patients with Crohn’s disease (CD)." (PMID 29206869, 2017). "In conclusion, despite these considerations, we have shown that genetic variations in the TPMT gene could be useful for predicting thiopurine-associated leukopenia in Italian patients undergoing treatment." (PMID 40869181, 2025). "However, despite lower TPMT variant frequency, a higher prevalence of thiopurine-induced leukopenia was observed in Asian populations." (PMID 36768780, 2023). "TPMT polymorphisms were detected amongst five patients of whom 1 developed leukopenia." (PMID 34425754, 2021). "Interestingly, TPMT seems to be of particular relevance in Caucasian, while in Asian population TPMT variants are less frequent, but the degree of leukopenia is more pronounced." (PMID 35582146, 2019). "The association between AZA-induced leukopenia and TPMT mutations is well-established." (PMID 29867468, 2018). "However, only about a quarter of inflammatory bowel disease (IBD) patients with thiopurine-induced leukopenia carry a TPMT mutation." (PMID 29206869, 2017). "Moreover, while the frequency of TPMT mutations is lower in Asians (1–3%) than in Caucasians (~10%), the occurrence of thiopurine-induced leukopenia is considerably higher in Asians." (PMID 29206869, 2017). "To interrogate the utility of using PrediXcan as a tool for detecting associations between genetic factors and azathioprine side effects, we aimed to determine whether the genetically predicted expression of TPMT or NUDT15 was associated with leukopenia or other known side effects of azathioprine." (PMID 41654962, 2026). "As proof of concept for using PrediXcan as a tool to define the association between genetic factors and azathioprine side effects, we aimed to determine whether the genetically predicted expression of TPMT or NUDT15 was associated with leukopenia or other known side effects." (PMID 36711487, 2023).
leukopenia (continued). "Thiopurine methyltransferase (TPMT), which was identified in the 1980s as playing a critical role in thiopurine metabolism, has variants associated with decreased enzymatic activity that may result in severe leukopenia." (PMID 36275829, 2022). "However, only approximately 20% of leukopenia cases can be explained by TPMT genetic deficiencies." (PMID 31024313, 2019). "The risk of leukopenia is increased in patients with high glutathione-S-transferase (GST) activity and low TPMT activity." (PMID 40868544, 2025). "Myelotoxicity is one of the most frequent reasons for drug withdrawal, and genetic polymorphisms in the TPMT and NUDT15 genes are well recognized as causing leukopenia." (PMID 40869181, 2025). "Azathioprine metabolism is also affected by mutations in the gene coding for thiopurine S-methyltransferase (TPMT), increasing the risk of toxicity, particularly in leukopenia." (PMID 38337432, 2024). "Thiopurine methyltransferase (TPMT), as a biomarker of thiopurine drug toxicity, effectively solves the problem of leukopenia in European and American populations." (PMID 37441519, 2023). "The most commonly observed dose-dependent adverse reaction is myelosuppression, primarily manifested as leukopenia, which occurs in up to 20% of IBD patients due to TPMT gene polymorphism." (PMID 35448412, 2022). "Thiopurine-induced leukopenia has been found to be associated with polymorphisms in thiopurine S-methyltransferase (TPMT) and Nudix Hydrolase 15 (NUDT15) genes, which encode TPMT and nudix hydrolase enzyme, respectively." (PMID 35548363, 2022). "In an illustration of the vital importance of pharmacogenomics in risk reduction, one study showed that the combination of TPMT and NUDT15 mutations accounted for ~50% of severe thiopurine-induced leukopenia." (PMID 36275829, 2022). "In this study, 19 (18.6%) of the 102 patients who had adequate thiopurine therapy experienced leukopenia, 11 patients (57.9%) had NUDT15 c.415C > T variants, 2 patients (10.5%) had NUDT15 c.52G > A variants while one (5.3%) had a TPMT variation." (PMID 35991642, 2022). "The results confirmed the findings of previous studies that the TPMT gene determines leukopenia and myelosuppression in European patients." (PMID 35448412, 2022). "Four of the five patients who were found to have TPMT c.719A > G (rs1142345) variation were analyzed for leukopenia." (PMID 35991642, 2022). "In Chinese 60 ALL children whose 6-MP initial doses were adjusted based on TPMT genotypes, NUDT15 c.415C>T variant was also one of the significant risk factors for thiopurine-induced leukopenia (WBC ≤ 2000/mm3)." (PMID 34442422, 2021). "Polymorphisms in thiopurine methyltransferase (TPMT) and Nudix hydrolase-15 (NUDT15) have been implicated as the predominant cause of thiopurine induced leukopenia in the Western countries and East Asia respectively." (PMID 34425754, 2021). "Recently, a novel association between CYP2A7 rs73032311 variant and 6-MP-induced leukopenia was reported in subjects with both WT NUDT15 and TPMT." (PMID 32611418, 2020). "In total, 3 SNPs exhibit significant association with 6MP-induced leukopenia (P < 0.01), including two well-reported variants at NUDT15 (rs116855232, P = 6.37 × 10−11) and TPMT (rs1142345, P = 0.003), respectively." (PMID 32265697, 2020). "In European populations, about 50% of thiopurine-induced severe cytotoxic adverse reactions such as severe neutropenia and leukopenia are explained by NUDT15 and TPMT genetic variants." (PMID 32611418, 2020). "In our study, we focus on the leukopenia events and on 6-MP dose, two indirect clinical measures of TPMT expression/activity." (PMID 33424606, 2020). "Although TPMT activity is less likely to be reduced in Asian patients, leukopenia occurs in 31–56% of patients even at AZA doses that are lower than those in Western countries." (PMID 31052430, 2019).
leukopenia (continued). "The aim of this study was to investigate the influence of NUDT15 R139C and thiopurine S-methyltransferase (TPMT) on azathioprine (AZA) induced leukopenia in patients with autoimmune hepatitis (AIH) and related cirrhosis." (PMID 31024313, 2019). "This indicates higher [leukocyte]*[azathioprine] product and therefore lower sensitivity for azathioprine-induced leukopenia in patients with higher TPMT activity." (PMID 29630648, 2018). "In this process, thiopurine S-methyltransferase (TPMT) metabolizes AZA to inactive molecules, and variant TPMT alleles (slow metabolizer) are associated with AZA-induced leukopenia with an elevation of 6-TGN level." (PMID 29867468, 2018). "TPMT genotype and tertiles of TPMT activity were compared to relapse free survival and occurrence of adverse events, particularly leukopenia." (PMID 29630648, 2018). "Of the 83 patients with wild type (TT) of TPMT*3C, 22 (26.5%) suffered leukopenia; of 4 patients with heterozygous (TC), 1 patient (25.0%) developed leukopenia." (PMID 29867468, 2018). "Previous studies have shown that lower TPMT activity is associated with higher 6-TGN and a higher likelihood of clinical response to thiopurine therapy, but also higher risk for leukopenia." (PMID 29206869, 2017). "RESULTS: Among confirmed cases, patients in the lowest tertile of TPMT predicted expression had significantly higher odds of developing leukopenia (OR = 3.30, 95%CI: 1.07–10.20, p = 0.04) versus those in the highest tertile; no other side effects were significant." (PMID 41654962, 2026). "CD patients with leukopenia had a higher frequency of the TPMT haplotype (p = 0.024)." (PMID 41153516, 2025). "In addition, azathioprine (AZA) is a commonly used drug to control CD, and our results indicated that PLAU was negatively correlated with TPMT, an enzyme involved in azathioprine (AZA) metabolism, and an important risk predictor for AZA-induced leukopenia." (PMID 39744064, 2024). "Among confirmed cases, patients in the lowest tertile (i.e., lowest predicted) of TPMT expression had significantly higher odds of developing leukopenia (OR=3.30, 95%CI: 1.07-10.20, p=0.04) versus those in the highest tertile; no other side effects were significant." (PMID 36711487, 2023). "Previous knowledge of TPMT genotyping is an important predictor of clinical response and may significantly reduce the occurrence of myelosuppression or thiopurine-induced leukopenia." (PMID 37959208, 2023). "No TPMT or NUDT15 variants were identified in five (26.3%) of the 19 patients who developed thiopurine-induced leukopenia." (PMID 35991642, 2022). "Of the 107 patients previously sequenced for a non-functional TPMT allele, 43% showed signs of anemia and leukopenia." (PMID 35448412, 2022). "Many recent studies from Asia have shown that the frequency of TPMT mutation is about 1.2–2.0% in the Asian population and was not predictive of the occurrence of leukopenia in this population." (PMID 35991642, 2022). "The remaining 18 patients who developed leukopenia had wild-type TPMT variations." (PMID 35991642, 2022). "Two other studies on Chinese patients with autoimmune diseases demonstrated that the polymorphism of TPMT was not clearly associated with AZA-induced leukopenia." (PMID 34084143, 2021). "The presence of TPMT polymorphisms did not correlate with the occurrence of leukopenia nor did it affect the maximal tolerated azathioprine equivalent dose." (PMID 34425754, 2021). "The odds of developing leukopenia in TPMT polymorphism were non-significant (0.77, 95% CI:0.0822 to 7.2134, P = 0.819) but were significantly higher in those with NUDT15 polymorphism (3.5933, 1.1041 to 11.6951, P value: = 0.0336)." (PMID 34425754, 2021). "One out of the five patients who had TPMT polymorphism developed leukopenia and one developed an idiosyncratic reaction whereas 25 of the 102 patients in no polymorphism group developed leukopenia and six developed idiosyncratic reactions." (PMID 34425754, 2021).